TNF (tumor necrosis factor)
Diseases named in the same sentence as TNF in open-access papers (continued):
Sharing a sentence is not in itself a finding about the gene and the disease.
neurodegenerative disease (continued). "There have been several TNF blockers, including etanercept, rivastigmine, adalimumab, golimumab, infliximab, and certolizumab, clinically approved to treat autoimmune and neurodegenerative diseases." (PMID 35651608, 2022). "A sub-state of reactive astrocytes induced by proinflammatory factors TNF, IL-1α, and C1q (“TIC”) has been implicated in many neurodegenerative diseases as a source of neurotoxicity." (PMID 35592112, 2022). "Necroptosis, a major driver of neuronal cell death and microglial dysfunction in neurodegenerative diseases, is initiated by the subsequential TNF-α induced activation of RIPK1, RIPK3, and MLKL." (PMID 36358573, 2022). "During neurodegenerative diseases, microglia are activated to mediate inflammatory responses, producing proinflammatory mediators (IL-6, TNF-α, iNOS, and COX2) and damaging neurons." (PMID 35418806, 2022). "TNF and IL-17 signaling pathways exacerbate neuroinflammation and neurodegeneration in various neurodegenerative diseases." (PMID 36339820, 2022). "Increasing the level of serum inflammatory cytokines such as interleukin-6 (IL-6) and tumor necrosis factor-α (TNF-α) in the elderly are considered risk factors for cardiovascular and degenerative diseases." (PMID 36160136, 2022). "Nevertheless, our findings are useful for searching for new (prophylactic) therapeutic approaches able to specifically target TNF-α to prevent PD and potentially other neurodegenerative diseases sharing TNF-α as a contributor to neurodegenerative progression." (PMID 36430754, 2022). "Inflammatory cytokines have been confirmed to mediate reactive astrocyte proliferation in neurodegenerative diseases, such as TNF-α and IL-1β." (PMID 35506163, 2022). "After ischemia and in humans with neurodegenerative diseases, brain TNF-α levels rise, and this rise is largely due to activated microglia." (PMID 36698776, 2022). "Numerous cytokines and chemokines of the TNF and IL superfamily are also increased in the cerebrospinal fluid (CSF) and serum of patients with neurodegenerative diseases, making them potential markers of disease onset, progression, or treatment efficacy." (PMID 34163421, 2021). "In an in-vitro model of neurodegenerative disease, it was confirmed that pro-inflammatory cytokines interleukin-1β (IL-1β) and TNF are elevated in the neurodegenerative disease state and induced neuronal death and apoptosis." (PMID 34877406, 2021). "Researchers have found that patients with neurodegenerative disease display higher concentrations of IL-6,TNF-α, IL-1β, and NF-κB." (PMID 34944391, 2021). "In contrast, dysregulated TNF production contributes to the pathogenesis of a variety of human diseases, including autoimmune disorders, cancer, neurodegenerative diseases and many others." (PMID 33579029, 2021). "Neuroinflammation is a process related to the onset of neurodegenerative diseases; one of the hallmarks of this process is microglial reactivation and the secretion by these cells of proinflammatory cytokines such as TNFα." (PMID 34671225, 2021). "For instance, previous studies have found that TNF signal inhibition in the central nervous system has an impact on normal brain function and neurodegenerative diseases." (PMID 34812409, 2021). "Since neuroinflammation is a key contributing factor for neurodegenerative diseases, the high levels of pro-inflammatory cytokines, such as tumor necrosis factor-alpha (TNF-α), interleukin (IL)-1β and IL-6, are found in the brain and CSF of patients." (PMID 34068550, 2021). "We also studied TNF-α and IL-1β, which are well-known inflammatory markers playing a key role in neurodegenerative disease." (PMID 34699347, 2021). "It increases proinflammatory cytokines, mainly Tumor Necrosis Factor-alpha (TNF-α), and contributes to neuroinflammation underlying several neurodegenerative diseases." (PMID 34941771, 2021).
neurodegenerative disease (continued). "Tumor necrosis factor α (TNFα) participates in the management of the immune response and in the protection from infections and has a crucial role in several autoimmune and neurodegenerative diseases." (PMID 33673707, 2021). "In this degenerative disease, the proinflammatory cytokines, such as tumor necrosis factor alpha (TNF-α) and interleukin-1 β (IL-1β), are involved in an imbalance between anabolic and catabolic agents." (PMID 34829953, 2021). "The expression of IL‐1β, IL‐6, TNF‐α, and iNOS is harmfully correlated with the development of neurodegenerative diseases." (PMID 33942523, 2021). "This review summarizes phytochemicals against TNF-α and their neuroprotective properties in various neurodegenerative diseases." (PMID 31991572, 2020). "Given “beneficial” and “deleterious” functions of microglia and TNF in neurodegenerative diseases, the clinical application of anti-TNF therapies remains very difficult." (PMID 32977412, 2020). "Tumor necrosis factor-alpha (TNF-α) is a potent pro-inflammatory cytokine that ameliorates neuroinflammation in neurodegenerative diseases." (PMID 32993092, 2020). "The dominant-negative TNF mutein XPro1595 has shown therapeutic activity in disease models of inflammatory and degenerative diseases." (PMID 32528961, 2020). "Altogether this indicates that the use of anti-TNF drugs is limited and contraindicative for several indications, including neurodegenerative diseases." (PMID 32528961, 2020). "The roles of INF-γ and TNF-α secreted by microglia have been reported in other CNS neurodegenerative diseases." (PMID 32382569, 2020). "Here, we analyze current literature describing the molecular processes involved in TNF synthesis and release from microglia, the resident immune cells of the CNS and the main source of this cytokine both in brain development and neurodegenerative diseases." (PMID 32977412, 2020). "Pro-inflammatory cytokines IL-17 and TNF-α are elevated in the serum of patients with neurodegenerative diseases, including ICH." (PMID 33424913, 2020). "In the present review, we summarized the evidence supporting the beneficial role of anti-TNF-α phytochemicals to prevent or slow the progression of various neurodegenerative diseases to modulate TNF-α induced neuroinflammation." (PMID 31991572, 2020). "TNF-α, which is released by reactive astrocytes and activated microglia, modulates oxidative stress and inflammation in neurodegenerative diseases." (PMID 31849636, 2019). "In this review, we evaluate the role of neuroinflammation in neurodegenerative diseases, focusing specifically on the role of TNF-α in neuroinflammation, as well as appraise current research on the potential of IMiDs as treatments for neurological disorders." (PMID 31867326, 2019). "It has also been reported that TNF-α produced by microglia exacerbates the neurodegenerative diseases." (PMID 31591353, 2019). "Cartilage degenerative diseases have an inflammatory component involving increased expression of pro-inflammatory factors such as TNF-α, IL-1β, and IL-6." (PMID 31666429, 2019). "In the future, a deeper understanding of the diverse molecular pathways of TNF signaling can contribute to the discovery of more specific and refined strategies to treat AD and other neurodegenerative diseases." (PMID 30778285, 2019). "Proinflammatory cytokines, including interleukins (ILs), transforming growth factor (TGF)-β1, and tumor necrosis factor (TNF)-α usually make neurodegenerative disease worse." (PMID 29382106, 2018). "TNF and IL-6 are two representative pro-inflammatory cytokines produced by microglia related to neurodegenerative diseases." (PMID 29807527, 2018). "In CA1 SR of 6 months old transgenic mice, we found significantly higher levels of the expression of the cytokines TNF-α, IL1β, as well as iNOS in astrocytes, confirming our and others’ results in TgCNRD8 mice and other models of neurodegenerative diseases." (PMID 30483118, 2018).
neurodegenerative disease (continued). "Increasing evidence has demonstrated that the proinflammatory factors such as NO, IL-1β, and TNFα contributed to neurodegenerative diseases." (PMID 29576855, 2018). "Altogether, these findings indicate the detrimental role of high concentrations of TNF and IL-1β in both forms of synaptic plasticity during neuroinflammatory and neurodegenerative diseases." (PMID 29861718, 2018). "Recent research has disclosed a role for chronic neuroinflammation in the pathophysiology of neurodegenerative diseases such as AD, and attention has focused the use of anti-TNF and TNF-modulating agents for prevention and treatment." (PMID 30544500, 2018). "We took into account for this classification that Th1 cytokines (TNF-α and IFN-γ) were mostly involved in chronic inflammatory disorders associated with ageing (such as cardiovascular, autoimmune and degenerative diseases)." (PMID 28138335, 2017). "The activation of microglia cells can produce NO, PGE2, TNF-α, IL-1β, and IL-6, which can contribute to the inflammatory reaction in neurodegenerative diseases." (PMID 29267220, 2017). "Wild-type rat astrocytes (TNF-activated) or from human SOD1G93A transgenic mice (a neurodegenerative disease model) were used to evaluate cell migration, Thy-1 receptor levels, signaling molecules, and reactivity markers." (PMID 28962574, 2017). "In contrast, the levels of IL-6, IL-1β and TNFα in the blood appear to be elevated in patients with both AD and PD, which is the evidence of systemic inflammation that accompanies both of these neurodegenerative diseases." (PMID 29211044, 2017). "Elevated levels of IL-6, IL-1β and TNFα often found in the blood of both AD and PD patients can be considered as the evidence of systemic inflammation accompanied both of these neurodegenerative diseases." (PMID 29211044, 2017). "Over the years, it has become obvious that selective inhibition of TNFR1 can be superior to global blockage of TNF in several models of degenerative diseases." (PMID 27755542, 2016). "Previous studies have reported TNF as the therapeutic target for neurodegenerative and also CAMs have been reported as targets for many neurodegenerative diseases." (PMID 27814735, 2016). "In particular, it increasingly rationalizes accounts of the usefulness of neutralizing excess cerebral levels of TNF in neurodegenerative disease." (PMID 27596607, 2016). "A considerable literature now exists on some compounds of this class, which are orally active, pass the blood-brain barrier (BBB) and improve outcome in neurodegenerative disease models by inhibiting TNF." (PMID 27596607, 2016). "CEBPD is responsive to many proinflammatory cytokines involved in the pathogenesis of neurodegenerative diseases such as interleukin-1β (IL-1β), interleukin-6 (IL-6), and tumor necrosis factor α (TNFα)." (PMID 26208701, 2016). "As a consequence of innate immune activation, an increased level of TNF is observed in many neurodegenerative diseases." (PMID 27814735, 2016). "Consistent with this idea is abundant evidence showing the importance of TNFα in mediating inflammation and apoptosis, characteristic of most neurodegenerative diseases." (PMID 27144978, 2016). "By pointing to excess extracellular glutamate as the target, these arguments greatly strengthen the case, put now for many years, to test appropriately delivered ant-TNF agents to treat neurodegenerative diseases in randomly controlled trials." (PMID 27596607, 2016). "Several studies have reported a relation between increased proinflammatory cytokines, as TNF-alpha, and neurodegenerative diseases, including PD." (PMID 26491600, 2015). "Excessive production of inflammatory mediators such as nitric oxide (NO) and proinflammatory cytokines like tumour necrosis factor-alpha (TNF-α) from activated microglia contributes to uncontrolled inflammation in neurodegenerative diseases." (PMID 26047814, 2015).
neurodegenerative disease (continued). "Both injury and neurodegenerative diseases increase the amount of TNFα in the brain and this contributes to neuronal death." (PMID 26345473, 2015). "We have analyzed chemokines CCL2, CCL5 and IL-8; as well as cytokines TNF-α and IL-1β as they are known to be involved in the pathogenesis of neurodegenerative diseases including PD." (PMID 26275153, 2015). "The cytokine TNF-α has been shown to play an important role in normal brain function as well as in neurodegenerative disease." (PMID 24675728, 2014). "For instance, microglia can compromise the neurogenic cascade during chronic stress, aging, and neurodegenerative diseases, by their release of proinflammatory cytokines such as IL-1β, IL-6, and TNFα." (PMID 24772353, 2014). "In patients with neurodegenerative disease, the CNS has increased numbers of activated microglia and astrocytes, and elevated pro-inflammatory protein levels, such as IL-6 and TNF-α." (PMID 23382826, 2013). "IL-1β and TNF-α are two of the inflammatory cytokines significantly elevated in neurodegenerative diseases such as AD, and they play a central role in initiating and regulating the cytokine cascades during inflammatory responses." (PMID 24455696, 2013). "For example, HIV-1 infected macrophage and DCs are important suppliers of proinflammatory cytokines, including TNF-α, IL-6 and IL-1β, which are etiologically relevant to HIV-1 associated neurodegenerative diseases (HAND)." (PMID 22693544, 2012). "On the other hand, chronic neuroinflammation, as seen in neurodegenerative diseases like PD, slows down the generation of neuroblasts, which is, at least in part, due to chronically increased TNF-α levels." (PMID 22892385, 2012). "TNFα and IL-6 are the proinflammation cytokines that are dependent on p38 signaling for their production, which has implications in neurodegenerative diseases." (PMID 21533102, 2011). "Pro-inflammatory cytokines such as IL-1β and TNF-α play an important role in mediating neuronal death and neuroinflammation in various neurodegenerative diseases." (PMID 21034511, 2010). "The impact of systemic infection on the progression of neurodegenerative diseases has been documented, and several circulating cytokines (interferon-γ and TNF-α) have been proposed to be important mediators." (PMID 18470306, 2008). "CASP3, TNF, and IL6 are involved in processes such as apoptosis, oxidative stress, ROS formation, axonal transport defects, and age-related signaling pathways associated with diabetic complications in multiple neurodegenerative diseases." (PMID 41601963, 2026). "Microglia play a crucial function in the inflammatory factor signaling pathway in neurodegenerative diseases, including influencing the balance of pro-inflammatory [interleukin (IL)-1 β and tumor necrosis factor-alpha (TNF-α)] and anti-inflammatory factors (IL-4 and IL-10)." (PMID 40271180, 2025). "Compound 4b can be considered as a lead compound or candidate in the treatment of neurodegenerative diseases because of its remarkable NO-inhibitory activity, potent inhibition against the release of TNF-α and IL-6 and possibly good permeability through the blood–brain barrier." (PMID 40286027, 2025). "In a variety of neurodegenerative diseases, the inflammatory response triggered by xenobiotics, chemicals, beta-amyloids, etc., is driven by inflammatory and pro-inflammatory cytokines and chemokines (TNF-alpha, IL-6, etc.)." (PMID 40332055, 2025). "Our data further support the involvement of caspase-4 in the activation of various neuroinflammatory markers, including t-tau, VEGF, TGF-β, TNF-α, and IL-6, in response to P. gingivalis-LPS in both SH-SY5Y and HMC3 cells, all of which are associated with neurodegenerative diseases." (PMID 40497980, 2025). "Similarly, many studies have reported that SIRT6 suppresses TNF-α in a neurodegenerative disease model." (PMID 40508105, 2025).
neurodegenerative disease (continued). "Over-activation of microglia has been determined as a property of neurodegenerative diseases, leading to the production of various proinflammatory cytokines and neurotoxic substances, including interleukin-1β (IL-1β), IL-6, tumor necrosis factor-alpha (TNF-α), and nitric oxide (NO)." (PMID 38674503, 2024). "Among the hub genes, IL-10 hub genes may help to discover targeted therapies for neurodegenerative disease because IL10 reduces TNF-α production in PD and increases Brain-derived neurotrophic factor (BDNF) levels." (PMID 39432502, 2024). "Furthermore, pro-inflammatory cytokines such as IL-1β and TNF-α have been identified as major contributors to synaptic and neuronal pathology in fatal neurodegenerative diseases such as EAE and MS." (PMID 39766497, 2024). "TNF-α is a pleiotropic cytokine with a key role in the pathogenesis of neurodegenerative diseases; hence, its modulation could be critical for therapeutic purposes." (PMID 39287687, 2024). "In the same way, strength training for 6–12 weeks did not alter plasma IL‐1β, IL‐2, IL‐6 and TNF‐α concentration in healthy elderly adults and patients with chronic‐degenerative diseases, while 12 weeks of resistance training decreased muscle TNF‐α mRNA in frail elderly individuals." (PMID 37938877, 2024). "The M1 microglia cause the release of various inflammatory markers, including tumor necrosis factor-α (TNF-α) and interleukin-6 (IL-6), which may directly damage the CNS and lead to neurodegenerative diseases." (PMID 38473792, 2024). "TNF-α also plays a dual role by promoting and protecting against neurodegenerative diseases." (PMID 38891863, 2024). "TNF’s ability to increase ROS may be why it is found to play a role in so many neurodegenerative diseases." (PMID 36816125, 2023). "However, alterations in the levels of TNF-α can be detrimental and have been related to several autoimmune and neurodegenerative diseases." (PMID 37391534, 2023). "Therefore, the role of TNF-TNFRs signaling in autoimmune and neurodegenerative diseases such as MS has been demonstrated." (PMID 37138340, 2023). "Since TNF is upregulated in many ocular disorders and neurodegenerative diseases, it may be beneficial to attenuate TNF levels and TNF-R1 activity as a means to promote neuroprotection." (PMID 36816125, 2023). "Hence, selective targeting of TNF-TNFRs signaling holds great promise for treatment of MS as well as other inflammatory and neurodegenerative diseases." (PMID 37138340, 2023). "Interestingly, blocking TNFR1 signaling with ATROSAB prevented membrane-bound TNF from activating neuroprotective signaling via TNFR2, further explaining the ineffectiveness of anti-TNF as therapeutic in neurodegenerative diseases." (PMID 35651608, 2022). "Some studies reported that TNF-α and IL-1β could stimulate actin and played an important role in the process of neurodegenerative disease." (PMID 35866065, 2022). "Lactobacilli can ameliorate chronic inflammation by decreasing TNF-α expression and may help ameliorate neurodegenerative disease." (PMID 36034713, 2022). "The activity of neuroprotective and pro-inflammatory factors, namely, brain-derived neurotrophic factor (BDNF), interleukin-6 (IL-6), and tumor necrosis factor-α (TNFα), involved in the neuronal cell damage in neurodegenerative diseases, were assayed in isolated hypothalamus." (PMID 35889920, 2022). "Cultured microglia initiate a robust proinflammatory response when exposed to LPS, an agonist of toll-like receptors, resulting in an altered gene signature and release of proinflammatory cytokines (e.g., IL1b, TNF, and IL6), which are implicated in neurodegenerative diseases." (PMID 35526014, 2022). "TNF is a regulatory cytokine and is a critical signaling protein involved in the pathophysiology of various immune-mediated and inflammatory disorders, including neurodegenerative diseases." (PMID 34804701, 2021).